EPHA3 (EPH receptor A3)
Diseases named in the same sentence as EPHA3 in open-access papers (continued):
Sharing a sentence is not in itself a finding about the gene and the disease.
endometriosis (1 paper, 2019). The growth of functional endometrial tissue in anatomic sites outside the uterine body. "However, the related report on the function of EPHA3 in endometriosis progression is still under development, and further assessments focused on elucidating the underlying mechanism of EPHA3 in endometriosis are required." (PMID 31262977, 2019). "After successful assessment of the expression pattern of EPHA3 in endometriosis, the focus of the experiment then shifted to establishing an endometriosis mouse model." (PMID 31262977, 2019). "Taken conjointly, it is suggested that EPHA3 holds potential as a therapeutic target for the treatment of patients with endometriosis." (PMID 31262977, 2019). "The in silico analysis highlighted the ability of EPHA3 to suppress endometriosis via regulation of the mTOR signaling pathway." (PMID 31262977, 2019). "The current study aimed at predicting the function and clinical significance of EPHA3 in endometriosis, from which EPHA3 ranked highly in DEGs." (PMID 31262977, 2019). "The present study showcased functionality of the EPHA3 as the suppressor of endometriosis via its disruption in autophagy and apoptosis of macrophages through inhibition of the mTOR signaling pathway." (PMID 31262977, 2019). "Another vital finding in this experiment showcases the advantageous properties of EPHA3 in the autophagy of macrophages in endometriosis." (PMID 31262977, 2019). "After successful modeling, the uterine tissues of endometriosis mice presented with a low expression of EPHA3 and activated mTOR signaling pathway." (PMID 31262977, 2019). "On comparing with those of the normal group, it was observed that the mRNA and protein levels of EPHA3 in the endometrial tissues of mice in the endometriosis group significantly decreased, while the mRNA and protein levels of mTOR and the ratio of p-mTOR/mTOR increased (both P<0.05)." (PMID 31262977, 2019). "Additionally, in the current study, a negative correlation was evident between the mTOR signaling pathway and EPHA3, with emphasis on the role as a mediator in the pathogenesis of endometriosis." (PMID 31262977, 2019). "In conclusion, the evidence collected from our study supports the contribution of the EPHA3 in the treatment of patients with endometriosis by means of its promoting effects on macrophage autophagy and apoptosis through inactivation of the mTOR signaling pathway." (PMID 31262977, 2019). "In addition, an important finding of the present study was that EPHA3 was poorly expressed, while the mTOR signaling pathway was activated in the endometrial tissues in mouse models with endometriosis." (PMID 31262977, 2019). "However, the exact function of EPHA3 in human endometriosis remains unclear." (PMID 31262977, 2019). "Therefore, through increased expression of bax and fas and decreased expression of bcl-2 in this study, we hypothesized that EPHA3 promoted the apoptosis of macrophages, with evidence supporting the role of EPHA3 as a potential therapeutic target for the treatment of endometriosis." (PMID 31262977, 2019). "Overexpression of EPHA3 inhibited the activation of the mTOR signaling pathway, down-regulated bcl-2 expression, up-regulated the expression of Atg3, LC3-II/LC3-I, Beclin1, bax and fas, and also promoted the autophagy and apoptosis of macrophages in endometriosis mice." (PMID 31262977, 2019). "In addition to its aid in the survival of the endometriosis cells, an investigation conducted to examine the relationship between EPHA3 and the expression of signaling proteins flagged the suppression of several signaling proteins, including PI3K, STAT3 and BMX as a result of EPHA3 overexpression." (PMID 31262977, 2019). "However, the function of EPHA3 in endometriosis remains unknown due to the lack of studies primarily focusing on the efficacy of EPHA3." (PMID 31262977, 2019).
epilepsy (1 paper, 2017). A brain disorder characterized by episodes of abnormally increased neuronal discharge resulting in transient episodes of sensory or motor neurological dysfunction, or psychic dysfunction. "During the activation, various genes of our predicted EPH family have been identified to promote such biological processes, validating the crucial role of EPH family including our predicted genes EPHA3, EPHA4, EPHA5, EPHA7, and EPHB2 during epilepsy." (PMID 28255556, 2017).
fatty liver (1 paper, 2018). "To further determine which genes might play a significant role in the progression of fatty liver, we used real-time qPCR to detect the expression of 8 DEGs using clinical samples, including CD24, PZP, COL1A1, COL1A2, LUM, VCAN, THBS2 and EPHA3." (PMID 29769552, 2018).
follicular lymphoma (1 paper, 2015). Follicular lymphoma is a form of non-Hodgkin lymphoma characterized by a proliferation of B cells whose nodular structure of follicular architecture is preserved. "Furthermore, a truncated form of EPHA7 has been reported to act as a tumor suppressor in follicular lymphoma, and it would thus be interesting to study its potential role in lung tumor suppression in conjunction with EphA3 loss of function." (PMID 25713296, 2015).
Hepatic fibrosis (1 paper, 2025). The presence of excessive fibrous connective tissue in the liver. "First, we validated the protein expression of EPHA3 in two mouse models of hepatic fibrosis, and Western blotting results showed that increased EPHA3 protein expression correlated with the degree of hepatic fibrosis." (PMID 40406118, 2025). "WB results showed that the protein level of EPHA3 significantly increased in both mouse models of liver fibrosis." (PMID 40406118, 2025). "Finally, we only performed a simple expression verification in the mouse model of liver fibrosis and briefly examined the role of EPHA3 in LX2 cells." (PMID 40406118, 2025). "Therefore, we conducted a preliminary investigation on the role of EPHA3 in liver fibrosis." (PMID 40406118, 2025).
insulinoma (1 paper, 2019). "To better understand the molecular underpinnings of EphA2/A3 upregulation, we next tested if depletion of Ift88 mRNA resulted in similar EphA3 upregulation in an insulinoma cell line, Min6m921." (PMID 31831727, 2019).
invasive carcinoma (1 paper, 2020). A carcinoma that is not confined to the epithelium, and has spread to the surrounding stroma. "Interestingly, in contrast to EPHB2, the expression of EPHA3, a member of another subclass of the ephrin receptors, was significantly decreased in invasive carcinoma samples." (PMID 32899940, 2020).
lentivirus infection (1 paper, 2022). Virus diseases caused by the Lentivirus genus. "One week after lentivirus infection, DNA sequencing analysis revealed that de novo mutations were generated on the Epha3 gene targeted by sgRNA3 and sgRNA5." (PMID 37013864, 2022).
lung squamous cell carcinoma (1 paper, 2023). "When they were compared with the normal tissues, EPHA3 was strongly upregulated in kidney renal clear cell carcinoma (KIRC, p = 8.3 × 1011), and lung squamous cell carcinoma (LUSC, p = 4.2 × 104)." (PMID 36765579, 2023).
monoclonal gammopathies of undetermined significance (1 paper, 2017). "EphA3 mRNA and protein were evaluated in ECs of MM patients (MMECs), in ECs of patients with monoclonal gammopathies of undetermined significance (MGECs) and in ECs of healthy subjects (control ECs)." (PMID 28415715, 2017).
myeloid leukaemias (1 paper, 2021). "In myeloid leukaemias and other cancers, EphA3 has been identified as a regulator of stem cell abilities." (PMID 34359759, 2021).
non-small cell lung carcinoma (1 paper, 2017). A group of at least three distinct histological types of lung cancer, including non-small cell squamous cell carcinoma, adenocarcinoma, and large cell carcinoma. "However, high expression of EphA3 was reported to suppress the growth of non-small cell lung cancer." (PMID 28465671, 2017).
orofacial clefting (1 paper, 2021). "FOXE1 and EPHA3 are both orofacial clefting candidate genes and have not been associated previously with normal-range facial features." (PMID 33983923, 2021).
ovarian endometriosis (1 paper, 2023). A non-neoplastic disorder characterized by the growth of endometrial tissue in the ovaries. "Prior studies have suggested that EPHA3 plays a role in treating ovarian endometriosis, potentially promoting apoptosis and autophagy of macrophages via the inhibition of the mTOR signaling pathway and reducing oxidative stress." (PMID 37340323, 2023).
papillary renal cell carcinoma (1 paper, 2024). A rare subtype of renal cell carcinoma, arising from the renal tubular epithelium and showing a papillary growth pattern, which typically manifests with hematuria, flank pain, palpable abdominal mass or nonspecific symptoms, such as fatigue, weight loss or fever. "EphA3 independently influenced the prognosis of papillary renal cell carcinoma (KIRP)." (PMID 38952552, 2024).
rhabdomyosarcoma (1 paper, 2022). A rare aggressive malignant mesenchymal neoplasm arising from skeletal muscle. "According to their in vitro trials, the EPHA3 expression was suppressed in rhabdomyosarcoma cell lines that harbor chromosomal translocations, which are associated with enhanced aggressiveness and metastatic potential." (PMID 35563562, 2022). "It has been observed that enhanced interaction between EPHA3 and its ligand ephrin-A5/Fc in rhabdomyosarcoma modulates Rho GTPases, leading to a decrease in cell–fibronectin adhesion and migration toward stromal cell-derived factor 1 (SDF-1)." (PMID 35563562, 2022). "Similarly, these oncogenic effects are demonstrated in soft tissue sarcomas when EPHA3, EPHB2 and EPHB4 stimulate properties such as proliferation, increased motility, migration, invasion and metastasis of rhabdomyosarcoma and synovial sarcoma cells." (PMID 35563562, 2022).
steatosis (1 paper, 2022). Increased lipid within the cytoplasm of cells. "H&E staining revealed more severe steatosis and larger lipid droplets in the liver of the hypothalamic EphA3 knock-out mice." (PMID 37013864, 2022).
systemic sclerosis (1 paper, 2020). A chronic disorder, possibly autoimmune, marked by excessive production of collagen which results in hardening and thickening of body tissues. "However, the genes harboring intronic SNPs, ALK (rs4575680), EPHA3 (rs1512909), and TULP4, also known as TUSP (rs341137), have been implicated in CVD-related traits, such as blood pressure, arterial fibrillation, and systemic sclerosis." (PMID 33374401, 2020).
T cell lymphomas (1 paper, 2019). "Given its unique expression on malignant T cells, EphA3 has strong potential to serve as a therapeutic target for EphA3+ T cell lymphomas with minimal detrimental effects on healthy T cells." (PMID 31333644, 2019). "EphA3 has been of particular interest to the cancer research field as it was originally identified in an acute lymphoblastic leukemia cell line and expression can be detected in many T cell lymphomas but not generally in T cells from healthy individuals." (PMID 31333644, 2019).
tumor (118 papers, 2003 to 2025). "The RTK EPHA3 is critically implicated in tumor cells adhesion, migration, and intercellular communication." (PMID 41514539, 2025). "Given EphA3’s status as a tumor-associated antigen, it serves as an ideal target for use in combination with other CAR T cell therapies, either as a multitargeted approach or within a logic-gated system." (PMID 39111833, 2024). "The EPH receptor functions as a tumor formation inhibitor, and the depletion or mutation of the EPHA3 gene reduces its suppressive effect on tumor proliferation, thereby promoting tumor metastasis." (PMID 38233802, 2024). "Elevated protein levels of EPHA3 are associated with aggressive tumor characteristics and an unfavorable prognosis in HCC." (PMID 39617786, 2024). "EphA3, the first receptor found as a tumor-associated antigen, can be recognized by a CD4+ T cell clone in melanoma and this process stimulates selective immunoreactivity." (PMID 37637034, 2023). "Flow cytometry analysis showed clearly upregulated expression of EphA3 compared to minimal expression on the control ‘tumour-naïve’ cell line, consistent with preferential expression on tumour-associated fibroblasts." (PMID 37760615, 2023). "Treatment with an agonistic antibody caused the retraction of EphA3+ stromal cells in vitro and the disruption of the tumour stroma and vasculature in vivo, with a corresponding decrease in tumour growth." (PMID 36830852, 2023). "Among twelve protein kinases, EGFR, HER4, and EphA3 were associated with tumor recurrence status, recurrence-free survival (RFS) and overall survival (OS)." (PMID 32093644, 2020). "Among the Eph receptor family members, EphA2 and EphA3 have been identified as tumor-associated antigens (TAAs), and their epitopes can be recognized by both CD4+ and CD8+ T cells." (PMID 33288738, 2020). "EPHA3 is among the most frequently mutated RTKs in human lung ADCs, and has been assigned a candidate tumor suppressor role based on its mutation spectrum and findings from in vitro and in vivo studies." (PMID 25713296, 2015). "Tumor-suppressive effects of wild-type EPHA3 can be overridden by dominant negative EPHA3 somatic mutations." (PMID 25861239, 2015). "Notably, further analysis of clinical samples showed that overexpression of EphA3 was associated with tumor diameter (P <0.0001) and TNM stage (P =0.0017)." (PMID 38952552, 2024). "This suggests that wild-type EphA3 may inhibit cancer formation or progression, and somatic cancer mutations disrupt these tumor-suppressive activities." (PMID 38811954, 2024). "Also, EphA3 overexpression was associated with histological differentiation, tumor depth, lymph node metastasis, distant metastasis, and poor prognosis." (PMID 39839790, 2024). "Loss of EPHA3 expression was positively correlated with tumor size and TNM stage." (PMID 34445116, 2021). "Thus, these would impair activity, indicating that loss of EPHA3 activity will lead to cancer development and provide compelling evidence for a tumor‐suppressive role of EPHA3 in cancer." (PMID 30548122, 2019). "The reduction in receptor activity conferred by the point mutations of EPHA3 found in cancers, and ligand- and EPHA3-dependent apoptosis of tumor and stroma cells upon receptor agonist treatment suggested that wild-type EPHA3 has anti-tumorigenic properties in NSCLC." (PMID 27101199, 2016). "Furthermore, two of the amino acids targeted by mutations to define the EphA3 interface, V231D and N232I, are within the 8 amino acid sequence that is defined as the epitope through which the EphB4 H200 antibody acts to cause tumour cell death." (PMID 25831049, 2015).
tumor (continued). "Next, we have determined that the activation of the EphA3-mediated signaling increases the invasive potential of both BC cells and cancer-associated fibroblasts (CAFs) derived from BC patients, thus contributing to the cooperation between tumor and stromal cells in BC progression." (PMID 37434266, 2023). "Therefore, EPHA3 warrants further investigation as a therapeutic target in pHGG, while taking into account the K27M mutational status of the underlying tumor, which might enable new precision medicine efforts for this disease cohort." (PMID 30961526, 2019). "WES of one eyelid mBCC tumour–stroma pair identified 150 shared nonsynonymous mutations—representing 76.5% of all stromal mutations—including mutations in ATR, EPHA3 and GLI3." (PMID 41373535, 2025). "Western blot analyses demonstrated that HOC continued to exert significant inhibitory effects on EPHA3 network during tumor recurrence, though the magnitude of suppression varied among specific targets." (PMID 41514539, 2025). "Daily oral administration of HOC in a nude mouse NEPC xenograft model markedly suppressed the tumor expression of EPHA3 and BRN2, along with their downstream effectors EZH2, ASCL1, and DLL3 and neuroendocrine markers SYP and CHGA." (PMID 41514539, 2025). "This agent also prevents the proliferation of cancer cells and endothelial cells in the tumor vasculature by inhibiting EphA3 signaling." (PMID 40688499, 2025). "Altered expression of EPHA3 also correlates with tumor diseases, which is also true for the potential oncogene CREB5." (PMID 40699665, 2025). "Although B7-H3×CD3 and EPHA2/EPHA3 BsAbs and TsAbs are effective preclinically, clinical feasibility and off-tumor toxicity require rigorous validation." (PMID 41209565, 2025). "Numerous studies reported the EPHA3 overexpression in several malignancies, including PCa, where it correlated with high aggression and invasive tumor potential." (PMID 41514539, 2025). "Conversely, low expression and a tumor-suppressive role of EphA3 have been observed in small-cell lung cancer." (PMID 40688499, 2025). "Complete tumor clearance was observed in 5 out of 7 (71.4%) mice treated with EphA3 CAR T cells by day 20 post treatment and maintained to day 27 after which all mice were euthanized." (PMID 39111833, 2024). "Concordant with our study, previous studies have also shown EphA3 is prominently expressed around the tumor vasculature of GBM xenografts, a known stem cell niche in GBM39 and tumor stroma." (PMID 39111833, 2024). "In vivo experiments further confirmed that the VIM-AS1‒EPHA3 axis controlled tumor growth and the tumor microenvironment in HCC." (PMID 39617786, 2024). "Mutations that impair kinase function of Eph receptors, such as EphB2, EphA3, EphA5, are frequently found in cancer, suggesting a tumor suppressor role for Eph receptor forward signaling." (PMID 38811954, 2024). "Mice treated with EphA3 CAR T cells exhibited tumor eradication within 4 weeks after treatment, leading to a prolonged complete response and significantly increased overall survival." (PMID 39111833, 2024). "The result showed that the expression of EphA3 protein was significantly associated with metastases (TNM) stage (P =0.0017), tumor diameter (P <0.0001), and age (P =0.0030)." (PMID 38952552, 2024). "We next examined EphA3 expression on tumor biopsy tissues collected in the setting of primary or recurrent disease to determine the heterogeneity of expression within the tumors." (PMID 39111833, 2024). "Inhibition of EphA receptors using soluble EphA-Fc or EphA3-Fc has been shown to effectively hinder tumor angiogenesis." (PMID 38811954, 2024).